Y_RNA (Y RNA )
Gene: Miscellaneous RNA gene on chromosome 12 (70,906,917 to 70,907,018, forward strand). Ensembl gene ENSG00000207387.
Homologues: Orthologues: chimpanzee Y_RNA (98% identical), macaque Y_RNA (95% identical). Paralogues in human: RNY3 (92% identical), Y_RNA (92% identical), Y_RNA (91% identical), Y_RNA (90% identical), RNY3P1 (89% identical), Y_RNA (89% identical), Y_RNA (88% identical), Y_RNA (87% identical), RNY3P14 (86% identical), RNY3P16 (86% identical), Y_RNA (86% identical), RNY3P2 (85% identical), and 98 more.